RN7SL135P (RNA, 7SL, cytoplasmic 135, pseudogene)
Gene: Miscellaneous RNA gene on chromosome 8 (63,234,634 to 63,234,911, reverse strand). Ensembl gene ENSG00000241964.
Homologues: Orthologues: chimpanzee Metazoa_SRP (100% identical), macaque Metazoa_SRP (94% identical). Paralogues in human: RN7SL2 (79% identical), RN7SL145P (78% identical), RN7SL1 (78% identical), RN7SL296P (77% identical), RN7SL3 (76% identical), RN7SL482P (76% identical), RN7SL660P (76% identical), RN7SL88P (76% identical), RN7SL126P (76% identical), RN7SL326P (76% identical), RN7SL431P (76% identical), RN7SL566P (76% identical), and 702 more.